PGLYRP3 (peptidoglycan recognition protein 3)
Description:
Pattern receptor that binds to murein peptidoglycans (PGN) of Gram-positive bacteria. Has bactericidal activity towards Gram-positive bacteria. May kill Gram-positive bacteria by interfering with peptidoglycan biosynthesis. Also binds to Gram-negative bacteria, and has bacteriostatic activity towards Gram-negative bacteria. Plays a role in innate immunity.
Synonyms: PGLYRPIalpha; PGRPIA; PGRP-Ialpha
Tractability: Small molecule: a structure with a bound ligand is known. Antibody: UniProt places it where antibodies can reach, with high confidence; its Gene Ontology location is reachable by antibodies, with high confidence; UniProt predicts a signal peptide or a membrane-spanning region.
Gene: Protein-coding gene on chromosome 1 (153,297,116 to 153,312,952, reverse strand). Ensembl gene ENSG00000159527.
Subcellular location: Secreted
Pathways (Reactome):
Immune System: Antimicrobial peptides
Gene Ontology:
Molecular function: peptidoglycan binding; peptidoglycan immune receptor activity; protein binding; protein heterodimerization activity; N-acetylmuramoyl-L-alanine amidase activity; zinc ion binding
Biological process: antimicrobial humoral immune response mediated by antimicrobial peptide; defense response to Gram-positive bacterium; detection of bacterium; killing of cells of another organism; immune response; innate immune response; peptidoglycan catabolic process
Cellular component: protein-containing complex; extracellular region; membrane
Genetic constraint (gnomAD): Loss-of-function variants: 41 observed, 39.49 expected, observed/expected ratio (o/e) 1.04, 90% interval 0.81 to 1.35. The upper end of that interval is the gene's LOEUF score, 1.35, which puts it in group 5 of 6, group 1 being the genes least tolerant of losing a copy. Missense variants: 407 observed, 449.45 expected, observed/expected ratio (o/e) 0.91, 90% interval 0.83 to 0.98. Synonymous variants: 204 observed, 181.8 expected, observed/expected ratio (o/e) 1.12, 90% interval 1 to 1.26.
Homologues: Orthologues: chimpanzee PGLYRP3 (99% identical), macaque PGLYRP3 (96% identical), pig PGLYRP3 (77% identical), guinea pig PGLYRP3 (77% identical), mouse Pglyrp3 (73% identical), rat LOC134485743 (73% identical), rat Pglyrp3 (62% identical), Drosophila melanogaster PGRP-LE (26% identical), Drosophila melanogaster PGRP-SA (24% identical), Drosophila melanogaster PGRP-SB1 (24% identical), Drosophila melanogaster PGRP-LF (22% identical), Drosophila melanogaster PGRP-SD (21% identical), and 5 more. Paralogues in human: PGLYRP4 (67% identical), PGLYRP2 (30% identical), PGLYRP1 (23% identical).
Diseases named in the same sentence as PGLYRP3 in open-access papers:
PGLYRP3 is named in the same sentence as 14 diseases in open-access papers, as found by Europe PMC text mining. Sharing a sentence is not in itself a finding about the gene and the disease. The quoted sentences say what the papers report.
psoriasis (3 papers, 2011 to 2016). An autoimmune condition characterized by red, well-delineated plaques with silvery scales that are usually on the extensor surfaces and scalp. "Also, human Pglyrp3 and Pglyrp4 are genetically associated with psoriasis." (PMID 26727498, 2016). "PGLYRP2 protects mice against psoriasis-like skin inflammation and is required for the development of experimental arthritis, whereas PGLYRP3 and PGLYRP4 protect mice against atopic dermatitis." (PMID 23840689, 2013). "Thus, the role of PGLYRPs in animal models of inflammatory diseases is well established, but the role of PGLYRPs in human diseases remains unknown, except for the previously reported association of PGLYRP3 and PGLYRP4 with psoriasis." (PMID 23840689, 2013).
atopic dermatitis (2 papers, 2011 to 2016). "By contrast, atopic dermatitis-sensitive Pglyrp-deficient mice (Pglyrp3−/−, Pglyrp4−/− and Pglyrp2−/−Pglyrp3−/− mice) all had lower expression of FoxP3 mRNA in the affected ears compared to WT mice." (PMID 21949809, 2011). "Atopic dermatitis-sensitive mice (Pglyrp3−/−, Pglyrp4−/−, and Pglyrp2−/−Pglyrp3−/− mice) had increased expression of genes characteristic of B cells and T cells." (PMID 21949809, 2011). "Our results thus indicate that Pglyrp3 promotes efficient population of the skin with Treg cells in oxazolone-induced atopic dermatitis." (PMID 21949809, 2011). "To further study the role of IL-17 (Th17 cytokine) in high sensitivity of Pglyrp3−/− mice to oxazolone-induced atopic dermatitis, we determined the protein levels of an IL-17-induced chemokine, CXCL-1, in the ears of WT and Pglyrp3−/− mice." (PMID 21949809, 2011). "We demonstrate here that Pglyrp3−/− and Pglyrp4−/− mice develop more severe oxazolone-induced atopic dermatitis than WT mice." (PMID 21949809, 2011). "Pglyrp3 mRNA expression initially increased and later decreased in the atopic dermatitis model, and decreased in the contact dermatitis model." (PMID 21949809, 2011). "Pglyrp3−/− mice in the atopic dermatitis model also had significantly lower numbers of CD4+FoxP3+ Treg cells in the affected skin compared to WT mice measured by flow cytometry." (PMID 21949809, 2011). "In summary, our results indicate that in WT mice Pglyrp3 and Pglyrp4 promote efficient population of the skin with Treg cells in the experimental model of atopic dermatitis." (PMID 21949809, 2011). "To determine whether IL-17 is required for the high sensitivity of Pglyrp3−/− mice to atopic dermatitis, we compared the severity of ear inflammation in oxazolone-treated Pglyrp3−/− mice in which IL-17 activity was inhibited with neutralizing anti-IL-17 mAb." (PMID 21949809, 2011). "To further investigate the role of Treg cells in high sensitivity of Pglyrp3−/− mice to atopic dermatitis, we induced generation of Treg cells by application of vitamin D to the skin (which is known to induce Treg cells) together with the sensitizing allergen, oxazolone." (PMID 21949809, 2011). "Therefore, our results indicate that Pglyrp3 and Pglyrp4 are involved in controlling multiple functions of Treg and Th17 cells in the skin in atopic dermatitis." (PMID 21949809, 2011). "Because WT mice were able to limit skin inflammation in the atopic dermatitis model more effectively than Pglyrp3−/− and Pglyrp4−/− mice, we then tested whether this difference is due to impaired generation or function of regulatory T cells (CD4+FoxP3+ Treg) in Pglyrp-deficient mice." (PMID 21949809, 2011). "Pglyrp3−/− and Pglyrp4−/− mice (but not Pglyrp2−/− mice) develop more severe oxazolone-induced atopic dermatitis than wild type (WT) mice." (PMID 21949809, 2011). "Our results show that Pglyrp3−/− and Pglyrp4−/− mice (but not Pglyrp2−/− mice) are more sensitive to the development of experimental atopic dermatitis than wild type (WT) mice." (PMID 21949809, 2011).
colitis (2 papers, 2016 to 2019). Inflammation of the colon. "Interestingly, it was reported that PGLYRP-2−/− and PGLYRP-3−/− mice were highly sensitive to DSS-induced colitis than PGLYRP-1−/− and PGLYRP-4−/− mice, which had intermediate or low sensitivity, respectively." (PMID 31416116, 2019). "Notably, PGLYRP-3−/− mice had the most significant changes in their gut microbiota whereas PGLYRP-1−/− and PGLYRP-4−/− mice were less sensitive to colitis and had fewer alterations in the gut microbiota." (PMID 31416116, 2019). "Both PGLYRP-3 and NOD2 recognize the bacterial PGN and play a synergistic role in maintaining intestinal microbiota and inflammation as PGLYRP-3−/− NOD2−/− double-knockout mice were more sensitive to DSS-colitis than PGLYRP-3−/− or NOD2−/− single knockout animals." (PMID 31416116, 2019).
pneumococcal pneumonia (1 paper, 2018). A febrile disease caused by STREPTOCOCCUS PNEUMONIAE. "Collectively, PGLYRP3 seems to be dispensable for the antibacterial defense during pneumococcal pneumonia." (PMID 29449834, 2018). "Therefore, we analyzed the expression patterns of PGLYRP3 in murine AECs, AMs, and bone marrow derived neutrophils (PMNs) in vitro and investigated the role of PGLYRP3 in an in vivo pneumococcal pneumonia model using PGLYRP3KO mice." (PMID 29449834, 2018). "Additionally, the function of PGLYRP3 during Streptococcus pneumoniae-induced pneumonia was investigated in a murine pneumococcal pneumonia model using PGLYRP3KO mice." (PMID 29449834, 2018). "Therefore, we aimed in this study to investigate whether PGLYRP3 can modulate the development and the outcome of pneumococcal pneumonia in a murine pneumococcal pneumonia mouse model using PGLYRP3KO mice." (PMID 29449834, 2018).
Sepsis (1 paper, 2018). Sepsis is defined as life-threatening organ dysfunction caused by a dysregulated host response to infection. "Thus, PGLYRP3 seems to have no impact concerning the bacterial clearance of S. pneumoniae within the lung but it might have a minor antimicrobial function in the case of sepsis due to pneumococci." (PMID 29449834, 2018).
infection (3 papers, 2015 to 2020). The state of being infected such as from the introduction of a foreign agent such as serum, vaccine, antigenic substance or organism. "Nevertheless, we cannot fully exclude, that a change in the infection dose may have shown differences in these parameters due to PGLYRP3-deficiency." (PMID 29449834, 2018). "Nevertheless, we saw differences in the gene expression of PGLYRP3 upon infection of isolated primary AMs and PMNs." (PMID 29449834, 2018). "In that study, mice were intranasally treated with recombinant human PGLYRP3 followed by an infection with S. aureus." (PMID 29449834, 2018). "The expression pattern of PGLYRP3 was analyzed in vitro in primary mouse cells 6 h post infection with S. pneumoniae (NCTC 7978) with a multiplicity of infection (MOI) of 1 and were compared to the uninfected control." (PMID 29449834, 2018). "Therefore, we conclude that the host responds to the infection with S. pneumoniae by induction of PGLYRP3, but this pathogen might have evasion mechanisms like glycosidases, which may neglect at least the direct antibacterial effects of PGLYRP3." (PMID 29449834, 2018). "Upon infection with pneumococci no regulation of PGLYRP3 was measured in AECs, but an approximately 66- and 373-fold increase of PGLYRP3 was observed in PMNs and AMs, respectively." (PMID 29449834, 2018).
Tumor (2 papers, 2019 to 2021). "Finally, PGLYRP3, GAL, ADCYAP1R1 and LIF were selected to construct the Tumor Mutation Burden Immune Prognostic model (TMB-IP) using the following formula: TMB-IP score = (PGLYRP3*0.0988045135949462 + GAL*0.0483710471635067 + ADCYAP1R1*0.123387518699318 − LIF*0.121787959868336)." (PMID 33836680, 2021).
PGLYRP3 also shares sentences with these, for which no sentence is quoted: cancer (1 paper); cervical adenocarcinoma (1); cervical cancer (1); cervical squamous cell carcinoma (1); colorectal cancer (1); contact dermatitis (1); pneumonia (1).